U2AF1 (U2 small nuclear RNA auxiliary factor 1)
Diseases named in the same sentence as U2AF1 in open-access papers (continued):
Sharing a sentence is not in itself a finding about the gene and the disease.
cancer (continued). "Here, we identified splicing alterations associated with U2AF1 mutations across distinct cancers using DNA and RNA sequencing data from The Cancer Genome Atlas (TCGA)." (PMID 24498085, 2014). "Given the significant changes in cassette exons and alternative 3′ splice site events associated with U2AF1 S34F/Y mutation, we examined the sequences of 3′ splice sites that were preferentially used in U2AF1 S34F/Y mutated cancers." (PMID 24498085, 2014). "Although recurrent somatic mutations in the splicing factor U2AF1 (also known as U2AF35) have been identified in multiple cancer types, the effects of these mutations on the cancer transcriptome have yet to be fully elucidated." (PMID 24498085, 2014). "To further elucidate core effects of U2AF1 mutations on cancer biology, we aimed to identify common transcriptome alterations associated with U2AF1 mutations in distinct cancer types." (PMID 24498085, 2014). "For all 30 splicing events, the direction of splicing was the same in both cancer types, where U2AF1 mutation caused a shift to exon skipping or exon inclusion for the same splicing event." (PMID 24498085, 2014). "In summary, we found multiple genes including several known cancer genes with altered splicing in the presence of the U2AF1 mutation both in human cancer and in U2AF1 mutant transfected cells." (PMID 24498085, 2014). "U2AF1 mutations are major causes of the myelodysplastic syndrome and some cancers." (PMID 41404809, 2025). "Though less frequently found in cancers compared to U2AF1 mutations, U2AF2 mutations were recently identified to cause neurodevelopmental disorders (NDD) in patients presenting with overlapping cognition impairments, hypotonia, seizures, autistic features, and various behavioral disturbances." (PMID 41404809, 2025). "In addition, cancer cells with SF3B1 or U2AF1 mutations require the presence of the wild-type spliceosome to survive." (PMID 35053445, 2022). "Therefore, given the vulnerability of hematopoietic cells with spliceosome mutations, selectively targeting the U2AF1WT allele in heterozygous mutant cells has the potential to therapeutically induce cancer cell death in patients with U2AF1 mutations." (PMID 36139566, 2022). "In this case also, U2AF1 mutations are heterozygous and the retained wild-type allele is expressed, suggesting that mutant cancer cells may require the residual normal protein to be viable." (PMID 35053445, 2022). "U2AF1 is a splicing factor subunit that showed an association with various cancer types." (PMID 33772054, 2021). "Interestingly, some of the recently uncovered potential cancer genes with hotspot mutations, e.g., SPOP and U2AF1, appear to exhibit fewer traits characteristic of the typical oncogenes such as promoting cancer cell growth or conferring oncogene dependence." (PMID 28740126, 2017). "In addition, the wild-type (WT) U2AF1 allele is always retained in cancers with common U2AF1 mutations, including U2AF1S34F." (PMID 27776121, 2016). "Somatic mutation in U2AF1 may cause splicing changes of key cancer genes, resulting in altered gene function or altered pathways." (PMID 24498085, 2014). "Our studies on the mutant U2AF1 provide a mechanistic basis for this observation and suggest a role for mutations in the core splicing machinery for the increased levels of ‘noisy splicing’ which are observed in cancer." (PMID 25271374, 2014). "Although there are splicing changes that are associated with U2AF1 S34F/Y mutation in these cancer specimens, it is unclear if the splicing changes are caused by the mutation or if there are unknown genomic alterations that are also correlating with the splicing changes." (PMID 24498085, 2014). "To look at transcriptome changes associated with U2AF1 mutations in different cancer types, we used The Cancer Genome Atlas (TCGA) data that provide both somatic mutations at the DNA level and high-throughput sequencing of mRNA (RNA-Seq) in the same individual specimens across multiple cancer types." (PMID 24498085, 2014).
cancer (continued). "In cancer, recurrent mutations in splicing factors such as SF3B1, SRSF2, and U2AF1 are frequently observed, and these aberrations likely induce translational dysregulation associated with ORF dominance." (PMID 41596295, 2026). "Our strategy to abrogate the growth of the U2AF1 mutant cancer cells is to target U2AF1-UHM that binds with U2AF2 to form a dimer recognizing the 3’ splice site in pre-mRNA splicing." (PMID 38883705, 2024). "For example, a single missense mutation (Ser34Phe) in the zinc finger domain of the conserved splicing factor U2AF1 is common in different types of cancers, leading to the post-transcriptional splicing of β-globin and FXR1 mRNAs." (PMID 38763947, 2024). "Recurring mutations in genes encoding 3′ splice-site recognition proteins, U2AF1 and ZRSR2 are associated with human cancers." (PMID 38088204, 2024). "To understand the role of U2AF1S34F in cancer, we analyzed currently available sequencing data from lung ADC primary samples with U2AF1 mutations to identify co-occurring mutations in known lung ADC driver genes." (PMID 39314447, 2024). "Other splicing inhibitors such as sudemycin D6 or E7107 also display stronger cytotoxic effects on splicing factor–mutant cancer cells, including mutations in SF3B1 and other splicing factors such as U2AF1 and SRSF2." (PMID 37562845, 2023). "All three HCT116KO cells showed loss of rhythmicity for U2AF1, an important RNA splicing mediator gene, which also lost rhythmicity in SW620 and L1236 cells, as compared to their corresponding lower grade cancer cell lines." (PMID 35552415, 2022). "In this review, we summarize the current research regarding cancer hotspot mutations identified in spliceosome components acting at the very first step of splicing, namely the U1 snRNA, SF3B1, and U2AF1." (PMID 35053445, 2022). "Recent studies on cancer genomes have revealed that recurrent somatic mutations of genes encoding RNA splicing factors (e.g. SF3B1, U2AF1, SRSF2, ZRSR2) lead to altered splice site preferences, resulting in cancer-specific mis-splicing of genes." (PMID 33427197, 2021). "What the authors also found was AS in splice factors such as U2AF1, and several HNRNPs and SRSFs, which can alter global AS in the cell and thereby drug response and cancer progression." (PMID 34356101, 2021). "To understand how the cancer-associated U2AF1S34F mutation promotes MDS, we next compared independent RNA samples of SKM-1 cells expressing wild-type U2AF1 and S34F mutant U2AF1 using RNA sequencing (RNA-seq)." (PMID 34183647, 2021). "Since senescence is a cancer prevention mechanism, we also explored the expression changes of U2AF1 in diverse cancer types." (PMID 33274830, 2020). "Since 2011, recurrent somatic mutations have been identified in a number of spliceosome components in human malignancies through the Cancer Genome Project, such as U2AF1 (U2AF35), SRSF2 (SC35), SF3B1 (SF3B155 or SAP155), and ZRSR2 (URP)." (PMID 32905346, 2020). "As U2AF1 showed heterogeneous expression profile among various cancer types, such heterogeneity deserves further study." (PMID 33274830, 2020). "We found five out of 33 cancer types showed significant U2AF1 expression change between tumor and matched normal tissues." (PMID 33274830, 2020). "Knockdown of U2AF1 decreased cell migration in vitro supporting previous studies of this protein in cancer progression." (PMID 33330095, 2020). "In addition, U2AF1 is an important component of the major spliceosome that has been found frequently mutated and associated to the generation of particular splicing patterns in several pathologies, including the production of oncogenic splicing variants in cancer." (PMID 31561558, 2019). "Exome sequencing studies have revealed a restricted pattern of somatic mutations in U2AF1/U2AF2 and other genes involved in 3′ss recognition in cancer cells, including SF3B1, ZRSR2, SF1, SF3A1, PRPF40B, and SRSF2 (reviewed in7)." (PMID 26732650, 2016).
cancer (continued). "The altered splicing event in CTNNB1 in U2AF1 mutant cancers results in a shift toward splicing of a more proximal splice site in the 3′ UTR of CTNNB1." (PMID 24498085, 2014). "We used JuncBASE to identify alternative splicing events that were significantly differentially spliced between U2AF1 wild-type cancer samples and U2AF1 S34F/Y samples." (PMID 24498085, 2014). "In contrast, we find a smaller proportion of splicing changes upon U2AF1 wild-type induction to be similar to alterations in human cancers (15/1221, Fisher's exact test, P = 0.72)." (PMID 24498085, 2014). "U2AF1 S34F/Y cancers preferentially exhibit alterations in cassette exon and 3′ splice sites compared to the set of highly variable splicing events (chi-squared test, P = 6.6e-26)." (PMID 24498085, 2014). "Targeting PUF60 may complement therapies for cancers harboring splicing factor mutations (e.g., SF3B1, U2AF1)." (PMID 41596295, 2026). "Research has shown that certain components of spliceosomes, including U1 snRNA, SF3B1, and U2AF1, may be related to tumors, which are critically involved in cancer progression." (PMID 39507054, 2024). "U2AF1 S34F is known to alter alternative splicing and polyadenylation of cancer-relevant genes." (PMID 37487637, 2023). "No cancer-related genes were affected by 126 mis-splicing events strongly associated with U2AF1 mutation (q-value <0.01 by t-test)." (PMID 30194306, 2018). "When using SNVs only, most such genes were known cancer genes, such as U2AF1, IDH1, and DNMT3A in LAML (FLT3 SNVs cluster within five amino acids), AKT1 and KRAS in BRCA, BRAF and KRAS in COADREAD, IDH1 and PARG (poly (ADP-ribose) glycohydrolase) in GBM, and KRAS in UCEC." (PMID 25348067, 2014). "A Wilcoxon rank-sum test was performed on PSI values between cancers with or without U2AF1 S34F/Y mutations to identify splicing events that were significantly different between the two groups." (PMID 24498085, 2014). "Thus, U2AF1 in the CARNMT1 KO cells behaves similarly to the U2AF1 S34F/Y mutants, raising a fascinating question: Do these cancer-associated mutations mimic a cell state in which CARNMT1 activity is physiologically down-regulated to execute a specific splicing program?" (PMID 37673460, 2023). "Overall, our U2AF1 structure highlights how the intron is recognized early in the splicing process, and reveals how alternative splicing may arise due to specific mutations in U2AF1 associated with diseases, such as MDS and cancer." (PMID 32958768, 2020). "Interestingly, the snRNPs which are the core components of the spliceosome seem to be rarely affected in cancer, while several mutations could be found in some cancer patients only at the SF3B1, U2AF1 or SNRNP70 genes." (PMID 29439487, 2018). "Additionally, these splicing events have a >10% difference in the median PSI of cancers with no splicing factor gene mutation and cancers with U2AF1 S34F/Y mutations." (PMID 24498085, 2014). "In 21q22, we detected amplification of five cancer genes, including the transcription factors ERG and RUNX1 and the RNA binding protein U2AF1." (PMID 39421445, 2024). "In addition, 21 of these genes were eGenes almost universally across cancer types including five putative long non-coding RNAs, genes known to play a role in the immune response (ICOSLG, ERAP2) and U2AF1, which is involved in spliceosome function." (PMID 35725412, 2022). "Commonly, the core components of spliceosomes, U2AF1 and SF3B1, are altered in cancer." (PMID 34356101, 2021). "DHX8, EIF3G, RBM22, U2AF1 UPF1 and YBX-1 are also candidates therapeutic targets for cancer therapy because the tumor cell progression was strongly inhibited by the downregulation of these RBPs in cancer cells, including HCT116, SUIT2 and OE33 cells, but not in non-cancerous cells." (PMID 34202873, 2021). "Yet, the minimal U2AF1 UHM lacked the sites of MDS-associated mutations, which limited the smFRET investigations to relatively rare, cancer-associated mutations of U2AF2 (L187V and M144I)." (PMID 32343311, 2020).
cancer (continued). "To investigate whether the HMA-resistance-specific CNAs influence gene expression, we assayed the expression of 8 cancer-related genes by quantitative reverse transcription PCR (RT-qPCR) including BCL9, ARNT, ABL2, STK11, TCF3, SMARCA4, RUNX1, and U2AF1." (PMID 28052028, 2017). "Also, genes STAG2 and U2AF1 were detected as drivers in AML and SMC1A in distinct cancers by the IntOGen tool." (PMID 26886259, 2016). "Moreover, we have identified an edge relating the genes with transmembrane protein function with those from the spliceosome (U2AF1, and USP9X) and the cohesin complex (SMC1A and STAG2) that have an important role in cancer." (PMID 26886259, 2016). "This might be that U2AF1 promotes cancer progression through its non-classical role in translation regulation." (PMID 41153010, 2025). "Additionally, knockdown of U2AF1 also decreased the neutrophil dependent cancer cell dissemination in vivo, which has not been previously reported, supporting its role in the metastatic process." (PMID 33330095, 2020). "Moreover, we show that proliferation of cancer cells with U2AF1S34F is critically dependent on expression of the wild-type, but not the mutant, allele of U2AF1." (PMID 27776121, 2016).
tumor (30 papers, 2007 to 2025). "Quantification of differential splicing events between tumor clusters and normal tissues showed that clusters harboring mutations in U2AF1, RBM10, and CMTR2 had significantly more splicing alterations than WT tumors." (PMID 41198678, 2025). "Numerous mutation sites of U2AF1 have been discovered in both hematologic malignancies and solid tumors, indicating the broad significance of U2AF1 mutations in tumor pathogenesis." (PMID 36139566, 2022). "U2AF1 mutation can severely impair hematopoiesis, drive tumor progression, adversely affect disease prognosis, and promote leukemic transformation." (PMID 36139566, 2022). "Here, we review the current knowledge about the genetic characteristics of U1 snRNA, SF3B1, and U2AF1 somatic mutations and the mechanism by which they influence splicing decision and, as a consequence, tumor development." (PMID 35053445, 2022). "Although these studies have suggested that U2AF1 mutations are selected early during tumorigenesis, mutations in a single allele of U2AF1 that lead to a predilection for carcinogenesis and tumor progression are unexplained." (PMID 34183647, 2021). "Among three LUAD cases with U2AF1 mutations where more than one tumor region was profiled in the TRACERx study, the mutation was invariably present in all sequenced regions." (PMID 31836708, 2019). "We genotyped two tumor deposits from distinct anatomic sites in a patient with LUAD carrying both a U2AF1 S34F mutation and a ROS1 fusion." (PMID 31836708, 2019). "In recent years, recurrent hotspot mutations in the spliceosome components U1 snRNA, SF3B1, and U2AF1 have been identified across different tumor types." (PMID 35053445, 2022). "Spliceosome (RBMX, SRSF3 and U2AF1) was observed as one of the representative events in tumor molecular machinery." (PMID 33261069, 2020). "In this sense, our data unveiled a clear downregulation of U2AF1 in NFPTs compared to NPs, which might suggest that not only the mutational profile but also the expression pattern could be involved in the malignant behavior of tumor pathologies including NFPTs." (PMID 31561558, 2019). "As controls, we tested for correlations between the inclusion of these cassette exons and levels of U2AF1S34F mRNA, total U2AF1 mRNA, or percent tumor nuclei." (PMID 27776121, 2016). "Mutations in various splicing regulatory factors such as U2AF1, ZRSR2, SRSF2, SF3B1, and RBM10 have been described in multiple tumor types." (PMID 28105922, 2016). "In this study, U2AF1, DNMT3A, SF3B1, and EZH2 in the secondary tumor group was higher than that in the tumor‐free group, while the mutation rate of ASXL1, TET2, and KMT2D was higher in the tumor‐free group." (PMID 36727544, 2023). "Whole-exome sequencing of paired tumor/control DNA samples from MDS patients reveals that the recurrent splicing factor mutations frequently occur in the major components of E/A splicing complexes, including U2AF1, SF3B1, SRSF2, and ZRSR2." (PMID 36139566, 2022). "Not only did we confirm known oncogenes, but we also propose novel tumorigenic genes, such as BSDC1 and U2AF1, that could distinguish between tumor subtypes." (PMID 33087122, 2020). "U2AF1 and ZRSF2 rarely co‐occur and are considered mutually exclusive in bone marrow tumours, suggesting that either both variants may have occurred in different clones during the clonal evolution of the disease, or spliceosomal regulation in cells carrying both mutations has been severely altered." (PMID 40066790, 2025). "An increasing number of mutations at core spliceosome components, such as S3FB1 and U2AF1, or upregulation of specific splicing factors, such as SRSF1 and other members of the SR protein family, which are now considered oncogenes, have been intimately linked to tumour progression and malignancy." (PMID 33845831, 2021). "Two nodes of module 1,” U2AF1” and “BCL1”, are oncogenes and “NAB2” is a tumor suppressor and “VTI1A” is a fusion gene." (PMID 35525925, 2022).
tumor (continued). "Sanger sequencing covering the U2AF1 (exon 2 and 7) hotspots and SRSF2 (exon 1 and 2) was performed on DNA extracted from tumor tissue." (PMID 31426461, 2019). "In the external dataset GSE16088, DDX39A and U2AF1 were significantly highly expressed in tumor samples, and RAB20 was significantly lowly expressed in tumor tissues, and PPP1R3 was significantly highly expressed in tumor samples, which was inconsistent with the results in the GSE39262 dataset." (PMID 41153010, 2025). "Interestingly, the induction of cleaved PARP was not strongly induced by the downregulation of RBM22 and U2AF1, suggesting that some RBPs promoted tumor progression via a tissue-specific mechanisms." (PMID 34202873, 2021).